GMFG (glia maturation factor gamma)
Diseases named in the same sentence as GMFG in open-access papers (continued):
Sharing a sentence is not in itself a finding about the gene and the disease.
tumor (continued). "Considering the main function of GMFG in actin remodeling vital for cancer immunity, angiogenesis, cell division and motility, GMFG is supposed to have important roles in tumor development, while up to now, only two studies described the role of GMFG in cancers." (PMID 33863293, 2021). "Moreover, GMFG inhibition markedly suppressed tumor progression." (PMID 39207055, 2024). "GMFG may involve in the cancer immunity and hematopoiesis through interacting with different immunomodulators and cytokines, leading to different immune response status and tumor progression in different types of cancer." (PMID 33863293, 2021). "Therefore, GMFG may also act as a regulator of immunomodulators and a cytokine-responsive protein in modulating tumor immunity and hematopoiesis in addition to serving as an ADF-H protein in remodeling the actin cytoskeleton." (PMID 33863293, 2021). "IER2 also induces expression of ERS‐CAF marker genes and results in production of a pro‐tumorigenic paracrine GMFG signaling, which exert its biological function via directly binding to ITGB1 on tumor cells." (PMID 39207055, 2024). "Pericytes play a crucial role in tumor neovascularization; consistently, we observed a strong angiogenic signature (such as for ANGPT2, CAV1, PDGFA, THY1, EGFL6, and GMFG) in pericytes." (PMID 37853464, 2023). "GMFG was reported to modulate iron metabolism and TLR4 responses in macrophages which potentially benefit tumor clearance." (PMID 37287069, 2023). "The correlation between GMFG expression and immune cell infiltration was evaluated using TIMER, Tumor Immune Single-Cell Hub (TISCH) database, and IHC staining assays." (PMID 35845613, 2022). "In order to verify the difference in expression of GMFG between tumors and normal tissues, we used TIMER database to analyze the expression of GMFG in tumor and normal tissues of multiple cancer types." (PMID 34367945, 2021). "Decreased GMFG expression was correlated with poor prognosis, and the expression of GMFG was related to chemotherapy drugs sensitivity and clinical features including age, ER status, PR status, HER2 status and tumor size." (PMID 34367945, 2021). "In this study, data from the Cancer Genome Atlas (TCGA), Clinical Proteomic Tumor Analysis Consortium (CPTAC), Human Protein Atlas (HPA), and Genotype-Tissue Expression (GTEx) databases were used to analyze the expression of GMFG in pan-cancer and the correlation between clinical factors." (PMID 37372337, 2023). "Besides, the expression of GMFG was related to the age, ER status, PR status, HER2 status and tumor size, which further suggested that the expression of GMFG was correlated with the subtype and the growth of tumor." (PMID 34367945, 2021). "Importantly, interventions targeting GMFG signaling could disrupt the communication between ERS‐CAFs and tumor cells, and thus inhibit ERS‐CAF's cancer‐promoting function." (PMID 39207055, 2024). "Besides, the expression level of GMFG showed the significant negative correlation with tumor size (p=0.018)." (PMID 34367945, 2021).
cancer (11 papers, 2021 to 2024). A tumor composed of atypical neoplastic, often pleomorphic cells that invade other tissues. "For example, increased expression of GMFG was associated with increased drug sensitivity of cancer cells to cisplatin (r=0.26, p=0.044), cyclophosphamide (r=0.57, p<0.001), carboplatin (r=0.34, p=0.008) and epirubicin (r=0.37, p=0.004)." (PMID 34367945, 2021). "Furthermore, GMFG has been implicated in immune responses across various cancer types, exhibiting a positive association with immune regulation." (PMID 38281298, 2024). "GMFG was mainly involved in the immune response, protein binding and cytokine-cytokine receptor interaction pathways, and was positively associated with multiple immunomodulators in most cancers." (PMID 33863293, 2021). "Furthermore, we also evaluated the impact of GMFG on cancer immunity by analysis of the association between GMFG and immunomodulators." (PMID 33863293, 2021). "GMFG is mainly involved in immune response, protein binding and cytokine-cytokine receptor interaction pathways, and is positively associated with immunomodulators in most cancers." (PMID 33863293, 2021). "The significant associations between GMFG and immunomodulators show that GMFG modulates the migration, adhesion and activation of immunocytes through regulating immunomodulators, thus functions in the immune response of various cancers." (PMID 33863293, 2021). "Finally, IDO1 and the cytotoxic molecules including GZMA and PRF1 showed a positively stronger association with GMFG in most cancer types." (PMID 33863293, 2021). "In addition, high expression of GMFG was associated with early pathological stage in four cancers (BLCA, LUAD, SKCM, and THCA), but was correlated with advanced pathological stage in STAD." (PMID 33863293, 2021). "The previous study has designed to explore the impact of GMFG in pan-cancers and the results showed that GMFG was significantly upregulated in GBM." (PMID 35845613, 2022). "Glia maturation factor-γ (GMFG) regulates actin cytoskeletal organization and promotes the invasion of cancer cells." (PMID 35845613, 2022). "Previous studies have revealed that GMFG mainly regulated filamentous actin structures and promoted migration and invasion of cancer cells." (PMID 35845613, 2022). "The context-dependent expression of GMFG was also validated by a TCGA pan-cancer analysis which reveals a low expression of GMFG in LUAD and LUSC." (PMID 35383531, 2022). "GMFG regulates the re-organization of actin cytoskeleton, as well as dipeptides that drive invasion and migration of cancer cells." (PMID 35845613, 2022). "The GO analysis indicated that GMFG was mainly correlated with the biological processes of signal transduction, immune response and inflammatory response in all cancer types with the exception of BLCA, KIRC, LAML and DLBC." (PMID 33863293, 2021). "Our study demonstrates that the expression of GMFG varies in different cancers, and high expression of GMFG predicts different prognoses for different cancers." (PMID 33863293, 2021). "Another mechanism causing the different survival outcomes may be that GMFG appears strongly correlated with different immunomodulators including co-stimulators, co-inhibitors, ligands, receptors, cell adhesion and antigen presentation molecules in different cancers." (PMID 33863293, 2021). "GMFG was mainly involved in cytokine-cytokine receptor interaction, cell adhesion molecules and chemokine signaling pathways in most cancers except for THYM, PCPG, DLBC, LAML, BLCA, and KIRC." (PMID 33863293, 2021). "In the literature, GMFG promotes the process of angiogenesis, and the proliferation and motility of cancer cell through altering the actin cytoskeleton." (PMID 33863293, 2021). "In summary, we found that GMFG is differentially expressed in human cancers." (PMID 37372337, 2023).
cancer (continued). "By wound healing and chamber assays, we found that silencing GMFG reduced MDA-MB-231 cell migration and invasion ability, suggesting that high expression of GMFG in TNBC might contribute to cancer progression." (PMID 37372337, 2023). "However in breast cancer, GMFG is found to be poorly expressed in cancer tissues, dismal clinical outcome are detected in breast patients with low GMFG." (PMID 35383531, 2022). "A possible explanation for this result is that GMFG functions differently in different cancers." (PMID 33863293, 2021). "Taken together, that GMFG enhances both the cancer progression and the immune defense, and patients’ survival outcome may depend on the balance between the speed of cancer development and the ability of immune system against cancer tissues." (PMID 33863293, 2021). "For molecular function, GMFG was strongly related to protein binding in all cancers." (PMID 33863293, 2021). "High expression of GMFG predicted different prognoses for different cancers." (PMID 33863293, 2021). "As an example, we identified PPP1R16A as a CRC-specific gene with robust depletion of NDR cfDNA coverage in plasma samples from cancer patients as compared to healthy individuals, and GMFG as a blood-specific gene with greater coverage depletion in healthy blood plasma." (PMID 33850132, 2021). "What’s more, our study also provides the overlapping co-expression genes in the cytokine-cytokine receptor interaction pathways, future studies may investigate the interaction between GMFG and these cytokines to better understand the role of GMFG in cancers." (PMID 33863293, 2021). "As for co-stimulators, GMFG was highly associated with CD80 and CD28 in most cancers." (PMID 33863293, 2021). "Moreover, we found that GMFG had a significantly positive association with PD-1 and PD-L2, but not with PD-L1 in all cancers except for THYM, DLBC, LAML, and LIHC." (PMID 33863293, 2021). "Thus, GMFG may interact with PD-1 and PD-L2 to promote the immune escape and progression of cancers." (PMID 33863293, 2021). "Moreover, the associations of GMFG expression with OS and DFS were also investigated, and high expression of GMFG predicted worse OS in four cancers (GBM, LGG, LUSC, and UVM), and worse DFS for LGG and PRAD, but was associated with better OS in SKCM and THYM, better DFS in CHOL." (PMID 33863293, 2021). "Interestingly, the expression of GMFG was also obviously higher in THYM, DLBC and LAML than that in other cancer types, and GMFG was mainly enriched in the plasma membrane in most cancers, but was strongly concentrated on the nucleoplasm or extracellular exosome in THYM, DLBC and LAML." (PMID 33863293, 2021). "In terms of co-inhibitors, GMFG showed a positive relationship with PDCD1LG2 (PD-L2) and SLAMF7 in most cancers." (PMID 33863293, 2021). "Our study found that, compared with in normal samples, GMFG was increased in six cancers (GBM, KIRC, LGG, LAML, PAAD, and TGCT), but was decreased in three cancers (KICH, LUAD, and LUSC)." (PMID 33863293, 2021). "GMFG, a member of the ADF/cofilin superfamily of proteins, is mainly expressed in inflammatory cells and is involved in regulating the reorganization of actin in a variety of cells, including cancer cells." (PMID 37372337, 2023). "Despite accumulating molecules clarified in cancer tumorigenesis, neither the roles of GMFG and mechanistic details remain enigmatic." (PMID 35383531, 2022). "Interestingly, GMFG showed a significantly positive association with PD-1 and PD-L2, but not with CD274 (PD-L1) in most cancers." (PMID 33863293, 2021).
metabolic disorders (1 paper, 2021). "Furthermore, a study reported that GMFG modulates the iron metabolism and M2 polarization of macrophage via inducing mitochondrial ROS and serves as a novel therapeutic target in immune and metabolic disorders." (PMID 33863293, 2021).
GMFG also shares sentences with these, for which no sentence is quoted: lung adenocarcinoma (3 papers); clear cell renal cell carcinoma (2); kidney chromophobe (2); lung squamous cell carcinoma (2); bacterial infections (1); bladder urothelial carcinoma (1); bone tumor (1); breast tumor (1); colon adenocarcinoma (1); diffuse large B-cell lymphoma (1); lymphoid neoplasm (1); melanoma (1); mesothelioma (1); non-small cell lung carcinoma (1); pancreatic adenocarcinoma (1); paraganglioma (1); pheochromocytoma (1); prostate adenocarcinoma (1); rectum adenocarcinoma (1); sarcoma (1); skin cutaneous melanoma (1); stomach cancer (1); testicular cancer (1); thymoma (1); triple-negative breast carcinoma (1); uterine carcinosarcoma (1); uterine corpus endometrial carcinoma (1); uveal melanoma (1).